IL13 (interleukin 13)
Diseases named in the same sentence as IL13 in open-access papers (continued):
Sharing a sentence is not in itself a finding about the gene and the disease.
asthma (continued). "However, that systematic review included asthma patients in different severity from mild to severe, and it didn’t assess the possibility of periostin level as biomarker for anti-IL-13 treatments." (PMID 30703143, 2019). "The human anti-IL-13 antibody tralokinumab decreased the use of β-agonists and improved lung function, but no improvement in the Asthma Control Questionnaire 6 score was observed in moderate to severe asthma cases." (PMID 31284537, 2019). "Moreover, isolated human mast cells produce IL-13 upon IgE-crosslinking, and IL-13 and IL-4 expressing mast cells are found within the airway smooth muscle of asthma patients." (PMID 31191511, 2019). "The hypothesis that asthma may be associated with decline in OR2AG2 was therefore explicitly tested in human samples and in-vitro experimental set up with IL-13 induction." (PMID 31836740, 2019). "In other AAD models, specifically in murine asthma, airway goblet cell hyperplasia was found to be directly induced by Th2-derived IL-9, whereas IL-4, IL-5, and IL-13 independently induce goblet cell hyperplasia, though indirectly via neutrophilic granulocytes." (PMID 30845208, 2019). "In regards to T lymphocytes, Th2 cells are considered one of the central players in asthma pathogenesis, as long as these cells participate in and coordinate the onset and progression of the inflammatory response in asthma through the release of cytokines, especially IL-4, IL-5, IL-9, and IL-13." (PMID 31019244, 2019). "A more recent study performed in 2016 evaluated IL-13 levels in the blood of children being treated for respiratory symptoms following severe hRSV bronchiolitis and found that IL-13 could be used as a clinical asthma diagnosis marker." (PMID 31214165, 2019). "Asthma exacerbations are often triggered by air pollution including ozone and in a murine model of asthma, ozone exposure resulted in enhanced AHR and greater neutrophilic inflammation associated with increased BAL levels of TNF-α, IL-13, and HA." (PMID 31354743, 2019). "Put together, these data suggest that pendrin may be maximally expressed in severe asthma, since, in this pathological condition, IL-17, as well as IL-4 and IL-13, are abundant in the airway epithelia." (PMID 30744098, 2019). "IL-13 is overexpressed during allergic asthma attacks, augmenting canonical calcium mobilization pathways, enhancing calcium sensitization, and aggravating asthma presentation." (PMID 31637021, 2019). "This further highlights not only the complexity of type-2 inflammation in severe asthma, but also that the role of IL-13 in severe asthma exacerbations may be limited." (PMID 31315668, 2019). "Interestingly, although IL‐27 production was increased in the IfitmF–/– mice compared to WT in our asthma experiments, levels of Il4, IL‐5, IL‐13, IL‐6, IL‐10, IL17, and TNF‐α were all decreased." (PMID 30365177, 2019). "The clinical use of dupilumab, as well as selective anti-IL-13 drugs, has shown that blocking IL-13 is effective both for the treatment of asthma and atopic dermatitis and may be of use in other atopic conditions (e.g., severe contact allergy)." (PMID 30759882, 2019). "Some patients with uncontrolled asthma still have a high level of IL-13 even when treated by inhaled or systemic glucocorticoid, which is consistent with the hypothesis that IL-13 can contribute to steroid resistance." (PMID 30703143, 2019). "Deletion of IL-4 or IL-13 using monoclonal antibodies has shown a benefit on asthma control." (PMID 30834081, 2019). "Furthermore, IL-13 also functions as a driver of mucus hypersecretion in the airway epithelia in autophagy-related asthma." (PMID 32082074, 2019). "IL-13 also contributes to epithelial cell maturation and bronchial fibrosisin in asthma." (PMID 31092255, 2019). "Furthermore, there is a link between rhinovirus infection, elevated IL-13 levels and contributions of asthma." (PMID 30759882, 2019).
asthma (continued). "IL-4, IL-5, and IL-13 belong to Th2 cytokines, which play a fundamental effect in asthma." (PMID 30834081, 2019). "Several studies have shown that IL-13 is expressed in bronchial biopsies in patients with asthma." (PMID 31866859, 2019). "It showed anti-IL-13 antibodies could improve peak expiratory flow, decrease FeNO and asthma exacerbation." (PMID 30703143, 2019). "TMEM16A expression is controlled by pro-inflammatory stimuli, namely, by the Th 2 cytokines IL-4 and IL-13 and is shown to be induced by asthma-like conditions, that is, in ovalbumin-challenged mice, in pig airway tissues treated with histamine and in biopsies from asthmatic patients." (PMID 31732694, 2019). "This protective effect against infections has been observed also for other type 2 immune diseases when treated with biologics targeting the IL-4R complex, such as the anti-IL-13 antibody Lebrikizumab in asthma and AD and the IL-4Rα-blocking agent Pitrakinra in asthma." (PMID 31708926, 2019). "In an in vitro study, psoralen significantly suppressed T helper type 2 (Th2) cytokines such as IL-4, IL-5 and IL-13 and therefore regarded as a critical component of PF for its in vivo therapeutic effects on airway hyperresponsiveness and inflammation of asthma." (PMID 31827595, 2019). "Previous studies have indicated that the Th2 cytokines IL-4 and IL-13 play a part in asthma." (PMID 31151443, 2019). "Several anti-IL-13 mAbs (anrukinzumab, lebrikizumab, tralokinumab) have provided an opportunity to investigate the role of this cytokine in the pathophysiology of severe asthma, as well as assessing treatment response." (PMID 31866859, 2019). "The IL-4/IL-13/STAT-6 pathway is a key modulator of asthma pathophysiology." (PMID 31637021, 2019). "In asthma, the expression of DUOX1 increased, and the underlying mechanism of IL-13-mediated increase in superoxide levels is that autophagy pathway could direct DUOX1 to the apical surface of the airway epithelium." (PMID 32082074, 2019). "In addition, it would be of interest to investigate other classical targets in asthma disease and to compare the effects of NS preparations on the release of Th2 cytokines IL-4, IL-5, and IL-13 in in vitro models." (PMID 30333747, 2018). "Moreover, we show that LIGHT has distinct as well as overlapping activities in lung fibroblasts compared to TGF-β and IL-13, two molecules that are also thought central to tissue inflammation in asthma, IPF, or SSc." (PMID 29616048, 2018). "The meta-analysis of NHW and AA subjects in our childhood asthma GWAS found association with known asthma variants in IL1RL1 (rs10197862, adjusted p = 0.042), in IL13 (rs1295686, adjusted p = 0.043), and near the C11orf30-LRRC32 region (rs7130588, adjusted p = 0.005)." (PMID 30373671, 2018). "Elevation of IL-4, IL-5, IL-9, and IL-13 was noted in asthma cytokine alterations." (PMID 30423980, 2018). "In our previous study, Kangzhi syrup could decrease IL-13 level in BALF of asthma models (data published), which should contribute to the overall protective effects in the CVA model." (PMID 29951106, 2018). "Future work will establish whether miR-31 and miR-155 play also a role in other IL-13 related diseases such as asthma and atopic dermatitis as well as targeting other genes involved in UC." (PMID 29438285, 2018). "However, the ability of IL-4-, IL-5-, or IL-13-producing Treg cells in the development of asthma needs to be further investigated." (PMID 30013989, 2018). "Tralokinumab neutralizes IL‐13, a key respiratory cytokine that drives inflammation, airway hyper‐responsiveness, and excessive mucus production in impaired lung function, contributing to the severity and frequency of asthma attacks." (PMID 29164823, 2018). "Although allergic asthma has always been considered to be a Th2 disease with increased eosinophils and Th2 cytokines such as IL-4, IL-5 and IL-13, severe asthma related to clinical resistance may result from a mixed Th2/Th17 response." (PMID 29540228, 2018).
asthma (continued). "The US FDA has approved drugs for asthma (anti-IL-5 agents, including mepolizumab, reslizumab, benralizumab, and anti-IgE omalizumab); atopic dermatitis (anti-IL-4/IL-13 agent dupilumab), psoriasis (anti-IL-17 secukinumab and brodalumab), and chronic urticaria (anti-IgE and omalizumab)." (PMID 29707206, 2018). "We asked whether LIGHT could promote inflammatory and remodeling-relevant activity in HLFs and how this was similar to, or distinct from, IL-13 or TGF-β, two cytokines strongly implicated in the pathogenesis of asthma, IPF, and SSc." (PMID 29616048, 2018). "IL-13 is another key cytokine of asthma; it shows pleiotropic effects on multiple cells." (PMID 29316647, 2018). "Recently, some studies have showed that dupilumab, a new anti-IL4/IL13 approach, could decrease asthma exacerbation and improve lung function." (PMID 29751569, 2018). "Moreover, it has been shown, using model mice, that the actions of IL-13 on airway epithelial cells are critical for generating asthma-like phenotypes." (PMID 29642409, 2018). "Although some aspects of asthma in Fra2 TG mice could be ameliorated by blocking IL-13 signalling or by treatment with glucocorticoids, the phenotype was partially resistant to both treatments." (PMID 30233597, 2018). "The goal of the present study is to test whether nasal epithelial cells have similar antiviral and inflammatory responses to IL-13 treatment and rhinovirus infection, a condition mimicking virally induced asthma exacerbation." (PMID 29721720, 2018). "It has been described, together with POSTN and chloride channel accessory 1, as a gene-signature for Th2 asthma and mainly IL-13 asthma phenotype, but until our knowledge, SERPINB2 protein expression has only been studied in broncoalveolar lavage (BAL) and never before at a peripheral level." (PMID 29977241, 2018). "IL-4 and IL-13 are signature type 2 cytokines playing critical roles in the pathogenesis of asthma." (PMID 29642409, 2018). "As IP-10 is considered a biomarker for active rhinovirus infection in asthma, it is important to uncover if IL-13 has any impact on IP-10 production in both injured (basal cells maintained in submerged cell culture) and intact (ALI cultured well-differentiated cells) airway epithelial cells." (PMID 29721720, 2018). "Thus, LIGHT signaling can promote a specific inflammatory signature in lung fibroblasts that is complementary yet distinct from TGF-β and IL-13, two molecules thought to be central to lung fibrosis and dysregulation seen in asthma, IPF, or SSc." (PMID 29616048, 2018). "IL-4, IL-13 and other type 2 cytokines have long been known to be drivers of allergic asthma, and many studies have shown increased chemokine levels in the airways of patients with asthma compared to controls." (PMID 30463560, 2018). "Several genes linked to asthma are regulated by epigenetic mechanism, such as genes involved in T-effector pathways (interferon INF-γ, interleukin-4 (IL-4), IL-13, and IL-17), T-regulatory pathways (forkheadbox P3 [FoxP3]), and airway inflammation (arginase [ARG])." (PMID 29992143, 2018). "Many studies determined the effect of IL4, IL5 and IL13 in asthma pathogenesis there for making balance between TH1 and TH2 cytokines might be helpful in asthma management." (PMID 29743896, 2018). "The type 2 cytokines such as IL-4, IL-5, and IL-13 are key players in the pathogenesis of asthma." (PMID 29593738, 2018). "Genes such as HLA, IL13, IL33, thymic stromal lymphopoietin (TSLP) involved in Th2 pathway, IL-1 receptor–like 1 (IL1RL1), encodes ST2, and the receptor for IL-33 are associated with asthma onset." (PMID 29904594, 2018). "Therefore, inhibitors directed against IL-13 or IL-4Rα have been developed as new asthma therapeutics." (PMID 30500834, 2018).
asthma (continued). "Typically in asthma, cytokines released by Type 2 T helper (Th2) cells including interleukin-4 (IL-4), interleukin-5 (IL-5), and interleukin-13 (IL-13) as well as cytokines released by Type 1 T helper (Th1) cells such as interferon-gamma are considered to be the main cytokines triggered in asthma." (PMID 30333747, 2018). "Moreover, other researchers demonstrated that in asthma pathogenesis IL-4 can induce similar lung pathology to IL-13, but independent from IL-13 and that IL-13Ralpha1 regulates IL-4-induced responses." (PMID 28533556, 2017). "In addition, the IL-13 levels were increased in only the asthma/A(H1N1)pdm09 group after the infection." (PMID 28831046, 2017). "Since IL-13 plays a role in both the sensitization and the effector phase of of classical asthma, the data obtained from the IL-13 KO mice, hence reduced T-lymphocyte numbers and lower concentrations of systemic IgE, cannot fully explain the role of IL-13 in the effector phase." (PMID 28704401, 2017). "Epigenomic studies have identified methylation patterns specific to COPD (e.g., C10orf11 in lung), asthma (e.g., IL13, RUNX3, TIGIT in PBMCs) and IPF (e.g., CASZ1 in lung), although much work remains to characterize cell-specific changes and include more ARDS and PAH samples." (PMID 28774304, 2017). "Decreased IL13RA1 expression is surprising in the context of asthma but this could be due to a compensatory response to continued eosinophilia and IL13/IL4 exposure in the lung." (PMID 29228930, 2017). "Similarly, nasal expression profiling has been proposed for identifying individuals with IL13-driven asthma and a Th2-skewed systemic immune response." (PMID 28493984, 2017). "The immune pathological feature of asthma is a T helper (Th) 2 (Th2) polarization condition in the airway mucosa, in which Th2 cells overproliferate and overproduce Th2 cytokines, including interleukin (IL)-4, IL-5, and IL-13." (PMID 28760845, 2017). "Previous studies suggested that IL-13, which is a Th2-associated cytokine, could aggravate AHR in patients with asthma." (PMID 28243240, 2017). "In the present study, we examined the role of miR-34/449 and autophagy in airway inflammation and remodeling in a cohort of patients with asthma, in IL-13 induced lung epithelial cells in vitro, and in a murine model of OVA-induced airway inflammation in vivo and explored the underlying mechanisms." (PMID 28796252, 2017). "IL-13 induces characteristic changes in mRNA and miRNA expression patterns in airway epithelial cells, and it induced protein periostin that is secreted basally from airway epithelial cells and can be used as a biomarker for Th2 high asthma." (PMID 28057889, 2017). "To identify a novel mediator involved in asthma pathogenesis downstream of the IL-13 signals, we and others previously used DNA microarray to search for IL-13-induced molecules in human airway epithelial cells, finding that the SLC26A4 gene encoding pendrin is a downstream molecule of IL-13." (PMID 29359006, 2017). "A transcriptomic approach to understand epithelial activation in severe asthma has thus highlighted the need for better-targeted therapy to the peripheral airways in severe asthma, where the IL-13 disease signature persists despite treatment with currently available therapy." (PMID 28045928, 2017). "As macrolides also affect type 2-dominated inflammation in asthma, we hypothesized that macrolide therapy may attenuate IL-13 stimulated periostin production and inflammatory gene expression in human lung fibroblasts." (PMID 28219384, 2017). "It is known that both IL4 and IL13 are involved type 2 responses, in IgE production in asthma, rhinitis and in eczema, as well as in the cellular inflammation of the three diseases as well as in the regulation of the epithelial barrier function in the skin, the airways, and type 2 responses." (PMID 28598986, 2017).
asthma (continued). "These specific genes, whose expression was attenuated by clarithromycin after IL-13 exposure, were dominantly categorized as “extracellular region,” “plasma membrane,” and “defense response” genes, among which asthma-related CD40, NOS2, and CXCL1 were included." (PMID 28219384, 2017). "Indeed, unpublished data from our preclinical studies testing the efficacy of anti-IL-13 in a mouse model of asthma found this to be the case." (PMID 29034234, 2017). "Interestingly, in moderate to severe asthma patients, serum IL-13 was strongly positively correlated with blood eosinophil counts." (PMID 29034234, 2017). "IL-4, IL-5, and IL-13 are essential Th2 cytokines in driving the development of asthma." (PMID 28106744, 2017). "They found that IL-13 (a critical cytokine in asthma) could change the composition and quantity of BEC-derived EVs." (PMID 29311962, 2017). "Furthermore, those asthma patients with higher levels of nasal IL-5 and IL-13 prior to RV infection, tended to be those with higher nasal levels of IL-5 and IL-13 after infection." (PMID 28373098, 2017). "Th2-type cytokines, particularly interleukin-13 (IL-13), have been shown to orchestrate airway allergic inflammatory and remodeling processes, and anti-IL-13 agents have been highlighted for the treatment of asthma cases unresponsive to ICSs." (PMID 29155876, 2017). "Group 2 innate lymphoid cells (ILC2s) are a relatively newly discovered lymphocyte population that promotes features of allergic airway diseases including asthma and chronic rhinosinusitis through secretion of the type 2 cytokines IL-4, IL-5 and IL-13 among others." (PMID 28959799, 2017). "In a mouse model of house dust mite-induced asthma in which AMs are depleted using clodronate liposomes, Th2 cytokines, such as IL-4, IL-5, and IL-13, and inflammatory cytokines and eosinophil recruitment were increased in BAL fluid, suggesting an immunosuppressive role of AMs." (PMID 28751894, 2017). "Thus, in treatment-resistant severe asthma there appears to be an effective steroid response in central airways, which is less evident in peripheral airways where the IL-13 disease signature persists." (PMID 28045928, 2017). "We also demonstrated that MUC5AC and MUC5B form distinct extracellular domains and that IL-13 induces a heterogeneous gel, which could have implications for mucociliary clearance in asthma." (PMID 29186064, 2017). "Our results may indicate that suppression of either IL‐5 or IL‐4/IL13 is insufficient and it is necessary to suppress both Type‐2 cytokines such as IL‐5 and IL‐4/IL‐13 for the improvement of asthma control." (PMID 28474411, 2017). "This implicates that anti-IL-13 treatment could have a beneficial effect in patients with this asthma phenotype." (PMID 28704401, 2017). "Recently, ILC2s were found in the bronchoalvoelar lavage (BAL) and sputum of patients with asthma, and the proportion of IL-5+IL-13+ ILC2s in the sputum of patients with severe asthma was higher than that in corresponding samples from patients with mild asthma." (PMID 28271447, 2017). "IL-5 and IL-13 are important cytokines in the asthma by recruiting eosinophil and neutrophil." (PMID 28423665, 2017). "Thus, IL-33 production induces IL-5 and IL-13 release in asthma, cytokines that are produced by Th2 and ILC2 cells." (PMID 28262704, 2017). "Tofacitinib plus dexamethasone produced a greater effect than dexamethasone alone, with an additive effect on the inhibition of IL-13 and IFNγ production from asthma and healthy cells; this additive effect on IL-13 from healthy cells was only apparent at low dexamethasone concentrations." (PMID 27716212, 2016). "In addition to reduced type 2 cytokine protein levels in OVA‐driven asthma, diminished mRNA expression levels of Il‐5, Il‐13, and Il‐4 were observed in CD4‐enriched lung cells from LXRα−/−β−/− mice." (PMID 27621817, 2016).